IL13 (interleukin 13)
Diseases named in the same sentence as IL13 in open-access papers (continued):
Sharing a sentence is not in itself a finding about the gene and the disease.
asthma (continued). "In addition, since a previous study indicated that IL‐13 contributes more strongly to the pathogenesis of arising asthma than does IL‐4,43 we used IL‐13 instead of IL‐4 for the rest of the experiments." (PMID 33534941, 2021). "They found that a single exposure of IL-13 may induce DNA methylation changes in an asthmatic’s airway cells and contribute to various asthma phenotypes." (PMID 34525985, 2021). "Moreover, we found the concentrations of IL-4, IL-5, and IL-13 were increased 4.71-fold, 3.58-fold and 3.42-fold in serum samples of asthma patients compared to healthy controls, respectively." (PMID 34749662, 2021). "In patients with severe asthma, colonization with potentially pathogenic bacteria, as represented by combined abundance of Moraxella catarrhalis, Haemophilus sp and Streptococcus sp, correlated with BAL neutrophil percentage and BAL IL‐13." (PMID 33411348, 2021). "In 2000, Graham14 and others proposed for the first time that children with bronchiolitis are prone to develop asthma, which may be related to the hyper-function of Th2-derived cytokines (interleukin-4 (IL-4), IL-5, and IL-13)." (PMID 33514798, 2021). "OVA induces experimental asthma by downregulating let-7 miRNAs and IL-13 expression." (PMID 34566492, 2021). "Moreover, in an ex vivo model, IL-13 treatment in fibroblasts isolated from bronchial biopsies in patients with mild asthma and normal controls resulted in significant increase in collagen type-1 production, which consequently leads to reduced lung elasticity." (PMID 35003121, 2021). "Recombinant proteins of S. mansoni were associated with an increase in IL-10 and TGF-β, an increased frequency of regulatory T and B cells, and a reduction in the frequency of activated T lymphocytes that produce IL-4 and IL-13 in individuals with severe asthma and animal models." (PMID 33732246, 2021). "Interleukin 4 (IL-4) and IL-13 regulate Th2 cell proliferation and B cell production of allergen-specific IgE, while IL-5 drives eosinophilic inflammation, all key features of the allergic responses in asthma." (PMID 35387008, 2021). "An explanation for this may be that the blockade of IL-13 alone is inadequate to achieve asthma control due to overlapping roles with IL-4." (PMID 33669458, 2021). "The worsening in asthma control may have been attributed to targeting of IL-23 leading to an increase in Th2 mediators, such as IL-13, thereby resulting in increased smooth-muscle tone within the airways." (PMID 35126131, 2021). "mRNA expression levels of IL4, IL5, and IL13 are increased in sputum cells from asthmatic patients in comparison to controls and can be used as molecular biomarkers to categorize patients into T2-high and T2-low asthma endotypes similarly." (PMID 33513844, 2021). "Changes due to an IL-13-induced asthma phenotype and infection with human rhinovirus 16 were evaluated based on cellular remodeling, temporal measurements of cytokine secretion (independently measured from the epithelial layer and media efflux) and neutrophil behaviors." (PMID 34178414, 2021). "The production and release of epithelial cytokines, including IL-33, IL-25, and TSLP, lead to the recruitment and activation of ILC2, which secretes mediators, such as IL-5 and IL-13, that augment allergic inflammation in the pathogenesis of virus-induced asthma exacerbation." (PMID 35008429, 2021). "IL‐13 is considered an archetypal T2 cytokine central to the clinical disease expression of asthma." (PMID 33411348, 2021). "Interleukin (IL)-4, IL-13, IL-5, and Th2 cytokines have a significant role in asthma development." (PMID 35046828, 2021). "Therefore, while IL-4 and IL-13 are now clinically validated therapeutic targets for the treatment of asthma, there is a clear need to improve current strategies, with the goal of reaching long-term cost-effective therapeutic effects." (PMID 33976140, 2021).
asthma (continued). "Recent studies suggest that eosinophil-derived IL-13 may play a more prominent role than IL-4 in the establishment of allergic inflammation in mice models of asthma." (PMID 34829186, 2021). "Towards this end, we retrieved four data sets of a murine model of ovalbumin‐induced asthma and four data sets of IL‐4‐stimulated or IL‐13‐stimulated bronchial epithelial cells from the GEO database as well as one data set from a previously published murine asthma model." (PMID 33960626, 2021). "Our data suggest that AHR may be more dependent on IL-13 than IL-4 in this chronic asthma model, and can be prevented upon prophylactic dual vaccination against IL-4 and IL-13." (PMID 33976140, 2021). "Moreover, IL-13 plays a key role in immune-related diseases such as asthma, pulmonary fibrosis, and ulcerative colitis; therapies for these diseases targeting IL-13 are being explored." (PMID 34201539, 2021). "Furthermore, in animal models and human epithelial cells, exogenous SP-A is shown to attenuate asthma-related factors and protect against IL-13-induced inflammation in asthma." (PMID 34484180, 2021). "IL13, IL4, IL4RA, FCER1B and ADRB2 are susceptible genes of asthma and atopy." (PMID 34243801, 2021). "The pathogenesis of asthma is predominantly attributed to the excessive immune response of T helper cell type 2 (Th2) and the production of substantial amounts of inflammatory cytokines [interleukin 4 (IL-4), IL-5, and IL-13]." (PMID 34737744, 2021). "In particular, IL-13 plays a key role in asthma, allergy, fibrosis and other pathological processes sustained by eosinophils whereas IL-9, initially described as T cell growth factor, is a pleiotropic cytokine linked to tumor immunity, immunity to pathogens, allergy, and autoimmune disease." (PMID 33146828, 2021). "Moreover, it is noteworthy that IL-9 which is a Type II cytokine behaved differently from other Type II cytokines (IL-4, IL-5, and IL-13) and was associated with an increase in ACE2 expression in sputum of asthma patients." (PMID 35111161, 2021). "Measurement of gene expression of the most important cytokines that drive T2-inflammation, specifically IL-4, IL-5, and Il-13, in induced sputum could be applied as a reliable biomarker for the identification of T2-high asthma." (PMID 33513844, 2021). "Airway samples in asthma have dysregulated TGFβ, as well as IL-13." (PMID 34332619, 2021). "Dupilumab is the first dual IL-4/IL-13 biologic approved for asthma treatment." (PMID 35126131, 2021). "It is located on chromosome 5q31 within the T helper 2 (Th2)-cytokine locus including IL-5, IL-4, IL-13, and it could contribute to tissue-specific Th2 inflammation in asthma and allergic diseases." (PMID 33925009, 2021). "Moreover, MDD has been shown to stimulate the production of cytokines, including IL-13 and IL-6, both of which are also strongly involved in asthma pathogenesis." (PMID 34566951, 2021). "Notably, a manifestation of disease symptoms considered extensively as hallmarks of asthma is directly or indirectly related to the overproduction of IL-4, IL-5, and IL-13." (PMID 33649900, 2021). "It is possible that the risk of one SNP involved in the IL-4/IL-13 pathway was not sufficient to result in profound changes in asthma susceptibility, just as our genetic associations have shown." (PMID 33810791, 2021). "Hypermethylation of IL-13 from airway epithelial cells at location 5q31 is seen in asthma." (PMID 34566492, 2021). "In addition, children and young adults with asthma manifest Type-2 high airway inflammation that is driven predominantly by allergy, IL-4 and IL13." (PMID 34261543, 2021). "MK2 and 3 are kinases activated by p38α; MK2/3 inhibitors or knockout of MK2/3 in mice reduced the production of IL-6 and IL-13 (two cytokines implicated in asthma) but not IL-5, IL-9 or GM-CSF in response to IL-33." (PMID 32103032, 2020). "Th2 cells could secrete IL-4, IL-5, and IL-13 to trigger asthma symptom, including increased eosinophil infiltration and AHR." (PMID 33343229, 2020).
asthma (continued). "Thus, IL-4 and IL-13 are factors that aggravate the inflammatory response in asthma, and there are also many studies that have achieved control of Th2-type asthma by preparing IL-4 and IL-13 antibodies." (PMID 33192556, 2020). "Furthermore, dexamethasone restored IL-13-induced miR-181b downregulation and inhaled corticosteroid treatment increased miR-181b in plasma from asthma patients." (PMID 33255348, 2020). "As it has been known that changes in airway epithelial cell differentiation, driven in part by IL-13 are essential in asthma, miRNAs are known to regulate cell differentiation in various systems and could contribute to epithelial abnormalities in asthma." (PMID 32770056, 2020). "Furthermore, new and emerging biologic therapies for severe asthma are cytokine-based (anti-IL-4, IL-5, or IL-13) and mostly target Th2-mediated pathways." (PMID 33574813, 2020). "The anti‐interleukin 13 (IL‐13) monoclonal antibody lebrikizumab improves lung function in patients with moderate‐to‐severe uncontrolled asthma, but its effects on airway inflammation and remodelling are unknown." (PMID 32909660, 2020). "BPA exposure might affect the immune system by releasing some pro-inflammatory mediators, including cysteinyl leukotriene, MAPK1, prostaglandin D2, and IL-13, which might be related to the development of asthma." (PMID 31906378, 2020). "However, combined administration of ascorbic acid and calcitriol in ineffective doses significantly decreased IL-13 levels in comparison with the asthma group (42.13 ± 0.37 vs. 50.5 ± 1.85 pg/mL, p = 0.02)." (PMID 31942829, 2020). "While they reported that serum SIRT1 levels were increased in OVA-sensitized and challenged mice model, SIRT1 levels were decreased in lung tissue, and more IL-4, IL-5, and IL-13 in BALF were found in the ovalbumin-induced asthma mouse model compared to the controls." (PMID 32823491, 2020). "The 298 unique DEGs from asthma cases in response to IL-13+IL-17A treatment were enriched for “cadherin binding” (adj Pcases = 9.0 × 10−7, Pcontrols = 0.067), while the 2717 unique DEGs from controls were enriched for “enzyme binding” (adj Pcontrols = 8.4 × 10−4, Pcases = 0.11)." (PMID 32690065, 2020). "Subsequently, Th2 cells produce cytokines related to asthma, such as IL-5, IL-4 and IL-13." (PMID 32397396, 2020). "However, ICS has broad effects, whereas lebrikizumab specifically inhibits IL‐13; so these data mechanistically implicate IL‐13 in subepithelial fibrosis in human asthma." (PMID 32909660, 2020). "Asthma has been mimicked in vitro by exposing the epithelium to interleukin-13 (IL-13)." (PMID 32570945, 2020). "However, significant positive correlations between both IS IL-4 and IL-13 protein level and IS eosinophil count in the asthma group were observed (r = 0.76, p = 0.006 and r = 0.68, p = 0.02, respectively)." (PMID 33203095, 2020). "IL-13 also enhances airway remodeling in asthma by inducing the transformation of bronchial fibroblasts to myofibroblasts; in addition, it promotes hyperplasia of goblet cells, stimulates proliferation of airway smooth muscle cells, and induces collagen deposition." (PMID 32019141, 2020). "In the Mexican-mestizo population, SNPs neither CNVs in IL4 nor IL13 are associated with asthma susceptibility or involved in plasma cytokine levels." (PMID 32366038, 2020). "In particular, therapeutic strategies that could ensure an optimal engagement of PD-1 on ILC2s would directly reduce asthma pathogenesis, notably IL-5-mediated eosinophil recruitment and IL-13-dependent mucus metaplasia in the respiratory tract." (PMID 32778730, 2020). "However, as part of pre‐specified secondary analyses, lebrikizumab reduced subepithelial fibrosis, a novel finding suggesting a role of IL‐13 in a fundamental aspect of airway remodelling in human asthma." (PMID 32909660, 2020).
asthma (continued). "However, dectin-1 signaling was also shown to be associated with CD4+ T cell production of IL-4, IL-13, and IFN-γ to a lesser extent, suggesting an interplay between Th2 and Th17 responses in fungi induced asthma." (PMID 33324573, 2020). "Thus, the differential transcriptional responses to IL-13 and IL-13+IL-17A in ASMCs from asthma cases and controls were enriched for smooth muscle-specific processes and immune dysregulation, two cardinal features of asthma." (PMID 32690065, 2020). "Moreover, IL-13 plays a key role in airway inflammation and is conceivable for asthma patients—this was evidenced with demonstration of an anti-IL-13 clinical test." (PMID 32397290, 2020). "Exposure to rOPN could induce the expression of Tgfβ1 and the release of TGF-β1, IL-5, IL-13, and phosphorylated Smad3 in a mouse model of virus-induced asthma exacerbation." (PMID 32009132, 2020). "Expression profiles reassembled in nasal and bronchial brushings, were specific to asthma independently of atopic status, and clustering analysis identified Th2-high and low subjects differentiated by expression of 70 genes (such as IL-13, IL-5, periostin, CLCA1, SERPINB2)." (PMID 32292784, 2020). "For example, inhibition of stearoyl-coenzyme A desaturase (SCD) in mice contributed to the development of airway hyperresponsiveness, while SCD1 gene expression was suppressed in bronchial epithelial cells in patients with asthma due to the effects of IL-4 and IL-13." (PMID 32395125, 2020). "This unique immune response is characterized by the production of the allergy-associated T helper cell type 2 (Th2) and Th17 cytokines interleukin 4 (IL-4), IL-13, and IL-17 that drive IgE, eosinophilia, airway hyperresponsiveness and other manifestations of asthma." (PMID 32485866, 2020). "IL-4 and IL-13 play a central role in the pathophysiology of asthma and could be very promising and appropriate targets for specific and effective new therapies." (PMID 32019141, 2020). "However, mmu-let-7a is markedly suppressed in Th2 cells, allowing IL-13 expression and stimulating the typical type 2 response of asthma pathology." (PMID 33488613, 2020). "This demonstrates that initiating treatment of T2 inflammation with anti-IL5 or an agent which blocks IL4 and IL13 for subjects with asthma and/or atopic dermatitis who also have CSU, CSU symptoms may be improved." (PMID 32944029, 2020). "Therefore, the researchers concluded that ILC2s contributed to allergic airway inflammation in asthma by producing IL-5 and IL-13 to the same extent as Th2 cells." (PMID 32397396, 2020). "In addition, IL-13 leads to subepithelial fibrosis, which contributes to airway remodeling in severe asthma." (PMID 33046682, 2020). "The roles of IL-4 and IL-13 in orchestrating the pathogenesis of asthma may help to explain the relationship between high FeNO levels and airflow limitation." (PMID 32824775, 2020). "Therapies that target IL-13 (anti-IL-13 antibodies) have been developed, such as lebrikizumab and tralokinumab however, they show inconsistent or only modest effects in treating severe asthma exacerbations in phase 3 clinical trials." (PMID 32724101, 2020). "Furthermore, Th2-specific IL-4 and IL-13 cytokines were produced by bronchial epithelial cells via STAT3-dependent allergic inflammation in asthma." (PMID 33374928, 2020). "T-cell differentiation to the TH2-subtype, the isotype switch towards IgE and effects on goblet cell hyperplasia and smooth muscle contractility are prevented by blocking IL-4 and IL-13 simultaneously, which may result in improved asthma outcomes." (PMID 31395084, 2019). "These genes have been demonstrated to influence a number of key components of asthma pathology, including eosinophil and T cell migration, production of Th2 cytokines (IL-4, IL-5, and IL-13), mast cell degranulation, IgE production, and airway hyperresponsiveness." (PMID 31221987, 2019).
asthma (continued). "Hence, the possibility of blocking or modulating IL-4 and/or IL-13 aroused great interest among researchers aiming to gain therapeutic benefit in asthma." (PMID 31355170, 2019). "Our study suggests that anti-IL-13 monoclonal antibodies could improve the management of uncontrolled asthma." (PMID 30703143, 2019). "Th2 cytokines such as IL-4, IL-5, IL-13, and IL-9 also have the same effects on asthma." (PMID 31143692, 2019). "In asthma patients, the Th2-related cytokines such as IL-4, IL-5, and IL-13 are usually increased." (PMID 31790411, 2019). "Two large phase 3 clinical trials, STRATOS 1 and STRATOS 2, explored the use of periostin and DPP-4 as biomarkers of IL-13-driven inflammatory patterns in patients aged 12–75 years with severe uncontrolled asthma treated with tralokinumab (300 mg s.c. every 2 weeks for 52 weeks) or placebo." (PMID 31866859, 2019). "Periostin is induced by IL-13 and has been studied as a biomarker of asthma." (PMID 30937129, 2019). "Niflumic acid prevents IL-13-mediated asthma by down-regulation of JAK2 and STAT6." (PMID 31569687, 2019). "Administered in remission phase, the effects of YPFS against asthma recurrence was determined by significantly reduced airway resistance, IgE level in serum, IL-5 and IL-13 production, peripheral eosinophils, and total cells in BALF, as well as remarkably alleviated pulmonary inflammation." (PMID 32076408, 2019). "Periostin (cut-off ≥50 ng/ml) was investigated as a predictive biomarker for therapeutic effect (measured as reductions in the exacerbation rate) in Phase III trials of the anti–IL-13 mAb lebrikizumab for the treatment of uncontrolled asthma, but proved inconsistent." (PMID 31315668, 2019). "Furthermore, increased numbers of IL-5+ and IL-13+ ILC2s were found in sputum after allergen challenge in asthma patients." (PMID 31443563, 2019). "This hypothesis is indirectly supported by the efficacy of dupilumab, which inhibits both IL-4 and IL-13 signaling mediated by IL-4Rα, in patients with severe uncontrolled asthma." (PMID 31866859, 2019). "The interesting results obtained in this experimental model may be more reflective of severe asthma which exhibit poor response to mAb anti-IL-13." (PMID 31866859, 2019). "Previous data showed that the anti-IL-13 arm in its bivalent form could sufficiently engage the target, as demonstrated by robust effects on IL-13 pathway biomarkers in asthma patients." (PMID 30616547, 2019). "However, asthma induced by IL-13 is closely related to the TH2-high asthma endotype that is driven by elevated IL-13 levels." (PMID 30397774, 2019). "Thus, we carried out a meta-analysis of RCTs to evaluate efficacy (asthma exacerbation, lung function, life quality and rescue medication use) and safety (adverse events) of anti-IL-13 antibodies for uncontrolled asthma." (PMID 30703143, 2019). "Therefore, the asthma profile that shows elevated IL-4, IL-5, and IL-13, characteristic of severe asthma in children, cannot be readily ascribed to adults." (PMID 31336954, 2019). "Indeed, the expression level of IL-13 producing ILC2 (IL-13+ ILC2) is negatively correlated with the degree of asthma control." (PMID 31737687, 2019). "Another very recent study, enrolling 1016 infants <12 months in 17 U.S. centers, confirms that high levels of cytokines inducing a Th2 immune response (IL-4, IL-5, IL-13, and Thymic Stromal Linphopoyetin) are significantly related to the onset of asthma in infants up to four years of age." (PMID 31195744, 2019). "Asthma is an eosinophilic/Th2 disorder, and novel therapeutics targeting Th2 cytokines (IL-4, IL-5 and IL-13) and IgE have achieved excellent improvements in disease control, although these therapeutics are applicable to only a sub group of patients in clinical studies." (PMID 31692453, 2019).